STAT3 (signal transducer and activator of transcription 3)
Diseases named in the same sentence as STAT3 in open-access papers (continued):
Sharing a sentence is not in itself a finding about the gene and the disease.
osteosarcoma (continued). "The sporoderm‐broken spores of Ganoderma lucidum (BSGWE) can also downregulate the phosphorylation of STAT3 to decrease the expression of PD‐L1, which can promote the apoptosis in osteosarcoma." (PMID 38800967, 2024). "Among the STAT family members, STAT3 stands out as an oncogene, frequently activated in various cancer types, particularly osteosarcoma." (PMID 38800967, 2024). "Up until now, there have been no studies examining the relationship between IL6, EGFR, and STAT3 and PD-L1 using immunohistochemical expression in osteosarcoma patient subjects." (PMID 38434518, 2024). "For instance, inhibition of the SRC/STAT3 signaling pathway by ameloblastin was shown to induce apoptosis and suppress chemoresistance of osteosarcoma cells." (PMID 38086608, 2024). "As a molecule that regulates cellular activity, c‐Myc inhibits apoptosis in osteosarcoma cells, while the STAT3/c‐Myc signaling pathway contributes to the expansion and development of osteosarcoma cells." (PMID 38800967, 2024). "Cisplatin is able to increase the expression of Nrf2 by activating STAT3 signaling, and the overactivation of STAT3/Nrf2 signaling mediates the enhancement of antioxidant capacity of cisplatin resistant osteosarcoma cells." (PMID 38469234, 2024). "Telocinobufagin blocks STAT3 signaling in non-small-cell lung cancer and osteosarcoma, while bufotalin induces ferroptosis by GPX4 degradation, thus inhibiting non-small-cell lung cancer progression." (PMID 39770538, 2024). "Both the folding and function of STAT3 are modulated by TRiC/CCT,129 and anticarin‐β induces apoptosis by inhibiting STAT3‐mediated antiapoptotic effects in osteosarcoma cells." (PMID 38363102, 2024). "Research has found that LRP8 have a high expression level in osteosarcoma and activates STAT3 which can promote the expression of PD‐L1 in osteosarcoma." (PMID 38800967, 2024). "In cases of osteosarcoma, miR-221 and miR-506-3p have been found to exhibit an opposite effect on STAT3 activity and influence P-pg expression." (PMID 39679367, 2024). "Currently, there is no report on miR-506-3p reversing doxorubicin resistance by targeting STAT3 in osteosarcoma." (PMID 38420199, 2024). "Of course, the specific mechanism of miR-506-3p in the regulation of JAK2/STAT3 signaling pathway in Doxorubicin-resistant osteosarcoma patients needs to be further investigated." (PMID 38420199, 2024). "Further proof of ferroptosis induction by impairing STAT3/NRF2/GPX4 signaling is observed in osteosarcoma cells, where STAT3 inhibitors reactivated ferroptosis and increased cisplatin sensitivity." (PMID 38341410, 2024). "Research indicates that targeting the STAT3 signaling pathway is a promising approach for osteosarcoma treatment, particularly in addressing programmed cell death and other forms of programmed cell death." (PMID 38800967, 2024). "STAT3 is the proto‐oncogene and cellular targets participating in the development of the osteosarcoma." (PMID 38800967, 2024). "In osteosarcoma cells, it has been suggested that STAT3 mediates apoptosis by inhibiting Bcl‐2 after apatinib treatment." (PMID 37502610, 2023). "By interacting with DNMTs, THAP9-AS1 modulates methylation patterns in the SOCS3 promoter region, paving the way for JAK2/STAT3 pathway activation and, consequently, osteosarcoma progression." (PMID 38140058, 2023). "DLGAP5 has been shown to activate the IL-6/JAK2/STAT3 signaling pathway, thereby promoting the proliferation and invasion of osteosarcoma cells." (PMID 37958803, 2023). "Specifically, the oncogenic activation driven by STAT3 intensifies osteosarcoma’s aggressive character." (PMID 38140058, 2023). "Activation of STAT3 upregulates the expression of target oncogenes and facilitates osteosarcoma metastasis." (PMID 37197432, 2023).
osteosarcoma (continued). "The long non-coding RNA (lncRNA) THAP9-AS1 binds to and promotes methylation of the SOCS3 promoter region with DNA methyltransferases (DNMTs) and activates the JAK2/STAT3 signaling pathway to facilitate osteosarcoma growth and metastasis." (PMID 37197432, 2023). "PYK2 secretion by osteosarcoma cells recruits bone marrow-derived cells (BMDCs) and induces M2 macrophage polarization by activating Stat3 in macrophage cells." (PMID 37197432, 2023). "Blocking of STAT3 can prolong the survival time of tumor-bearing mice by suppressing tumor growth and increasing Dox sensitivity in osteosarcoma." (PMID 37480115, 2023). "By blocking the STAT3/Nrf2/GPX4 signaling pathway, osteosarcoma cells become more susceptible to cisplatin." (PMID 37576601, 2023). "Recently, miR-221-3p derived from M2-polarized TAM exosomes was reported to promote proliferation and metastasis and aggravate the malignancy of osteosarcoma by regulating the SOCS3/JAK2/STAT3 axis." (PMID 37377390, 2023). "For example, excessive STAT3 activation can bolster osteosarcoma cell proliferation and strengthen cell resistance to adriamycin and cisplatin." (PMID 37628777, 2023). "These pathways have been shown to promote osteosarcoma cell proliferation, but only the Janus-activated kinase/STAT3 pathway can drive the migration of osteosarcoma cells." (PMID 36849442, 2023). "Previous research has indicated that piperlongumine inhibits the JAK2/STAT3 pathway to suppress osteosarcoma progression." (PMID 36814203, 2023). "We further detected the protein expression of TIPE1 and STAT3 in 20 osteosarcoma tissues by immunohistochemical staining." (PMID 36151091, 2022). "On the other hand, it has been suggested that STAT3 plays key roles in ferroptosis which demonstrates a new approach to attenuate drug resistance in osteosarcoma." (PMID 36618071, 2022). "The role of STAT3 in chemoresistance was further supported by data obtained from osteosarcoma samples from patients, namely, increased expression of p-STAT3, MRP (multidrug resistance protein), and MDR-1 (P-glycoprotein) correlated with chemoresistance." (PMID 35954425, 2022). "This abolished modification decreased STAT3 transactivation and expression, by which subsequently suppressed osteosarcoma malignancy." (PMID 36151091, 2022). "Irisin was shown to inhibit EndMT through the modulation of STAT3/Snail pathway in osteosarcoma and by mediating the PI3K/Akt/Snail signaling pathway." (PMID 36077366, 2022). "This shows that SIGLEC-15 inhibits tumor proliferation by affecting the activity of the STAT3/Bcl-2 signaling pathway, thereby affecting the apoptosis and pyroptosis of osteosarcoma cells." (PMID 36358792, 2022). "Additionally, increased STAT3 cytosolic level may suggest the inhibition of mTOR signaling as the crosstalk between these pathways has been implicated in several malignant diseases, e.g., osteosarcoma." (PMID 35163154, 2022). "We thus postulated that TIPE1 inhibits the tumorigenesis and progression of osteosarcoma by regulating PRMT1-mediated STAT3 expression." (PMID 36151091, 2022). "Taken together, these data showed that TIPE1 inhibits the malignant transformation of osteosarcoma through PRMT1-mediated STAT3 arginine methylation and ultimately decreases the development and metastasis of osteosarcoma." (PMID 36151091, 2022). "Aspergillus niger inhibits osteosarcoma cell growth and induces apoptosis by inhibiting the SRC/STAT3 signaling pathway in osteosarcoma." (PMID 36291659, 2022). "TBL1XR1 thus provides osteosarcoma cells with tumorigenic properties and promotes the recurrence of osteosarcoma in a STAT-3 signaling dependent manner." (PMID 35582537, 2022).
osteosarcoma (continued). "LIF promotes the stem cell properties of osteosarcoma through the NOTCH1 signaling pathway and enhances the growth and invasion of osteosarcoma by activating STAT3 signaling, while blocking STAT3 signaling can inhibit the development of osteosarcoma." (PMID 35740622, 2022). "The results showed that TIPE1 specifically decreased the expression level of total STAT3 and p-STAT3 in osteosarcoma cells, instead of the expression of total Jak2 and p-Jak2." (PMID 36151091, 2022). "This was the first study focused on drug-resistant osteosarcoma and revealed a novel approach to make osteosarcomas more sensitive to the drug by utilizing ferroptosis inducers or STAT3 inhibitors." (PMID 35402247, 2022). "miR-19 has also been found to promote the progression of osteosarcoma by targeting and downregulating Socs6 in association with Janus kinase 2 (JAK2)/signal transducer and activator of transcription 3 (STAT3) signaling." (PMID 35126805, 2022). "Previous work suggested that STAT3 was a powerful regulator of tumor immunosuppression, and activation of the JAK2/STAT3/PD-L1 signaling axis played a crucial role in the immune escape of osteosarcoma and cervical cancer." (PMID 36231093, 2022). "We reported that TIPE1 inhibited cell proliferation, migration and invasion in the carcinogenesis of osteosarcoma by inhibiting PRMT1-mediated STAT3 function." (PMID 36151091, 2022). "Recent studies have shown that the inducing ferroptosis by blocking STAT3/Nrf2/GPx4 signaling makes osteosarcoma cells more sensitive to cisplatin." (PMID 35774794, 2022). "Western blot results indicate that miR-331-3p affects the occurrence and development of osteosarcoma through the SOCS1/JAK2/STAT3 pathway." (PMID 36199788, 2022). "Knockdown of ANRIL in the osteosarcoma cell lines was able to increase the Cisplatin-induced chemosensitivity via the upregulation of miR-125a-5p and reduction of its target gene STAT3." (PMID 35755302, 2022). "Here, we report that TIPE1 is a novel STAT3 pathway regulator and a tumor suppressor in osteosarcoma." (PMID 36151091, 2022). "Another report also showed that PRMT1 can methylate and activate STAT3 and contributes to osteosarcoma progression." (PMID 36151091, 2022). "Another reported that Cos inhibited the proliferation, invasion, and metastasis of osteosarcoma by inhibiting the STAT3 signaling pathway." (PMID 34869312, 2021). "Taken together, NEAT1 promoted the liver and lung metastases of osteosarcoma in vivo through the miR-483/STAT3 axis." (PMID 33546665, 2021). "In this study, we firstly verified the anti-osteosarcoma effect of diosmetin in both Saos-2 and U2SO cell lines and determined it inhibited cell proliferation and promoted apoptosis of human osteosarcoma cells via STAT3/c-Myc signaling pathway." (PMID 34922636, 2021). "In the present study, overexpression of STAT3 enhanced the migration and invasion of osteosarcoma cells by increasing the expression of N-cadherin, Vimentin, Snail and reducing the expression of E-cadherin to subsequently promote the EMT process." (PMID 33546665, 2021). "The exposure of osteosarcoma cell lines (Saos-2, MG-63) to condition media from MSCs elevates IL-6 levels, which further activates the STAT3 signaling pathway, resulting in increased tumor growth." (PMID 34681692, 2021). "The activation of the STAT3 signaling pathway was identified as a major factor involved in the occurrence of osteosarcoma and the regulation of tumor proliferation and metastasis." (PMID 34168981, 2021). "How diosmetin affects ERβ or TrkB signaling pathways and their crosstalk with STAT3/c-Myc signaling pathway to inhibit osteosarcoma need to be further explored." (PMID 34922636, 2021). "In osteosarcoma cells, inhibition of STAT3 increases the sensitivity of chemotherapy‐resistant cells and eliminates drug efflux." (PMID 34129726, 2021).
osteosarcoma (continued). "We over-expressed STAT3 in U2OS cells (OE-STAT3) through lentivirus-mediated transfection to directly substantiate the finding that miR-483 inhibits the EMT in osteosarcoma cells by suppressing STAT3 expression." (PMID 33546665, 2021). "Another curcumin analogue, L48H37, also decreased the phosphorylation of JAK1, JAK2, JAK3, and STAT3 in osteosarcoma cells." (PMID 34867402, 2021). "OXY enhances pro-apoptotic proteins and reduces anti-apoptotic proteins in osteosarcoma cells, which induces apoptosis in the cancer cells through inhibition of the STAT3 signaling pathway." (PMID 33946346, 2021). "GK dose-dependently inhibits STAT3 phosphorylation and significantly reduces Survivin expression in osteosarcoma cells, thereby significantly inhibiting tumor growth." (PMID 34539403, 2021). "The JAK/STAT3 signaling pathway has been demonstrated to be a target to inhibit the growth and metastasis of osteosarcoma." (PMID 34552929, 2021). "In the present study, diosmetin shows anti-osteosarcoma effects by inhibiting the activation of STAT3/c-Myc signaling pathway, instead of relying on ERβ or TrkB signaling pathways." (PMID 34922636, 2021). "In summary, these results confirmed that NEAT1 promoted the EMT of osteosarcoma cells by upregulating STAT3 expression and increasing its phosphorylation, which was mediated by the inhibition of miR-483 expression." (PMID 33546665, 2021). "Relevantly, the treatment of osteosarcoma CSCs with cinobufagin, a steroid lactone used in Chinese medicine, was able to reduce their levels of IL-6, p-STAT3 and OPN, resulting in an attenuated stem-like phenotype and decreased tumor growth." (PMID 34198693, 2021). "For example, Tu and colleagues found that IL-6 secreted from mesenchymal stem cells (MSCs) activated STAT3 in osteosarcoma cells and promoted their survival and metastasis." (PMID 33546665, 2021). "So, the role of WP1066, a well-known inhibitor for STAT3 activation, in cell proliferation of osteosarcoma cells was also compared with that of diosmetin." (PMID 34922636, 2021). "Previous studies showed that STAT3 signaling pathway plays an important role in the inhibition of osteosarcoma proliferation by Apatinib." (PMID 34868934, 2021). "The lncRNA NEAT1/miR-483/STAT3 axis plays a crucial role in regulating the metastasis of osteosarcoma and potentially represents one appealing therapeutic target for osteosarcoma treatment in the future." (PMID 33546665, 2021). "Up-regulated STAT3 signaling has been previously found in human and canine osteosarcoma cell lines, and the effects of a small molecule inhibitor that prevented STAT3/DNA interaction, and further STAT3 cancer cell’s transcription has been documented." (PMID 33544704, 2021). "The NEAT1/miR-483/STAT3 axis identified in the present study played a crucial role in modulating the EMT in osteosarcoma cells, and a similar axis with different miRNAs as the mediator has been shown to participate in the progression of various tumours." (PMID 33546665, 2021). "It has been found that Interleukin 6 (IL-6) promotes epithelial-to-mesenchymal transition (EMT), stemness and chemoresistance in osteosarcoma cells through the hyperactivation of STAT3 through a mechanism mediated by osteopontin (OPN)." (PMID 34198693, 2021). "The Res administration (0–3 μM) decreases cytokine generation and suppresses JAK2/STAT3 axis to impair CSCs features in osteosarcoma via CD133 down-regulation." (PMID 34769099, 2021). "The low expression of STAT3 in osteosarcoma patients reduces recurrence after surgery and chemotherapy." (PMID 34681692, 2021). "FLLL32 is a diketone analog of curcumin that decreases DNA-binding activity and expression of STAT3 and induces apoptosis in osteosarcoma cell lines." (PMID 34671398, 2021).
osteosarcoma (continued). "To determine the involvement of STAT3 signaling in the anti-tumor effects of diosmetin on osteosarcoma cells, we examined the proliferation ability of Saos-2 and U2OS cells by applying diosmetin (0.3 μM) with or without IL-6 (20 ng/mL)." (PMID 34922636, 2021). "Those compounds possessed an inhibitory effect on the M2-macrophage polarization by suppressing STAT3 activation and preventing osteosarcoma progression and metastasis in osteosarcoma mice model." (PMID 33363016, 2020). "For example, IL-6 secreted by MSCs in response to paclitaxel or doxorubicin, resulted in the activation of STAT3 signaling pathway, promoting the growth of head and neck cancer, nasopharyngeal carcinomas as well as osteosarcoma." (PMID 33276524, 2020). "The compound inhibited constitutive and interleukin-6-induced STAT3 signaling and diminished the accumulation of STAT3 in the nucleus, blocking STAT3 DNA-binding activity in osteosarcoma cells." (PMID 32703212, 2020). "Han and colleagues have demonstrated that tumor associated macrophages (TAMs) have the ability to promote the migration and invasion of osteosarcoma (OS) cells by activating the STAT3/COX-2 axis and inducing epithelial mesenchymal transition (EMT)." (PMID 33299414, 2020). "More importantly for this study, miR-125b has been found to suppress osteosarcoma cell proliferation and migration by downregulating STAT3." (PMID 32161621, 2020). "Apatinib can inhibit tumor cell growth by blocking the VEGFR2/STAT3/Bcl-2 or Akt/GSK3β/angiogenin signaling pathways, suppressing tumor angiogenesis in osteosarcoma and anaplastic thyroid cancer, respectively." (PMID 32509141, 2020). "Mechanistically, they found SEs function as an activator of the NOTCH1 pathway through regulating the LIF/STAT3 pathway in promoting the progression of osteosarcoma." (PMID 32714929, 2020). "Another small molecule inhibitor, LY5, which inhibits homodimerization by blocking the phosphotyrosine site of the STAT3 SH2 domain, inhibited STAT3 activation by decreasing the cell viability of sarcomas, including osteosarcoma, ES, and RMS." (PMID 32754598, 2020). "In previous research, we demonstrated that apatinib inhibits PD-L1 presentation by targeting STAT3 in osteosarcoma." (PMID 33014879, 2020). "Another study has shown that apatinib weakens migration and invasion by inhibiting epithelial-mesenchymal transition and inactivating STAT3; in addition, apatinib decreases the expression of PD-L1 in osteosarcoma cells." (PMID 32587785, 2020). "In osteosarcoma cell lines, ML264 treatment found to inhibits the activation of STAT3 and proteins associated with EMT by decreasing KLF5 expression." (PMID 33424607, 2020). "In osteosarcoma, miR-125b was found to regulate STAT3 by downregulating MAP kinase kinase 7 (MKK7), which inactivates STAT3 via dephosphorylation." (PMID 31616462, 2019). "In conclusion, our data showed that SC, a cantharidin derivative, inhibited osteosarcoma progression in vitro and in vivo and abrogated the feedback activation of STAT3 induced by EGFR inhibition." (PMID 31422383, 2019). "We found that SC repressed cell viability and migration and induced apoptosis in vitro, while combined SC and erlotinib treatment enhanced osteosarcoma growth suppression by preventing feedback activation of STAT3." (PMID 31422383, 2019). "LY5, a small molecule inhibitor that antagonizes constitutive and inducible STAT3 activation, was shown to inhibit tumor cell migration and angiogenesis and to induce apoptosis in medulloblastoma, osteosarcoma, Ewing’s sarcoma, and rhabdomyosarcoma cells." (PMID 31422383, 2019). "Abnormal EGFR expression and constitutive STAT3 activation have been described in osteosarcoma cells in relation to disease progression and chemotherapy resistance." (PMID 31422383, 2019).